EIF2B1 (eukaryotic translation initiation factor 2B subunit alpha)
Description:
Acts as a component of the translation initiation factor 2B (eIF2B) complex, which catalyzes the exchange of GDP for GTP on eukaryotic initiation factor 2 (eIF2) gamma subunit. Its guanine nucleotide exchange factor activity is repressed when bound to eIF2 complex phosphorylated on the alpha subunit, thereby limiting the amount of methionyl-initiator methionine tRNA available to the ribosome and consequently global translation is repressed.
Synonyms: EIF2BA; EIF-2Balpha; EIF-2B; EIF2Balpha; EIF2B; VWM1
Tractability: Small molecule: a structure with a bound ligand is known; it has a binding pocket of medium quality. Antibody: its Gene Ontology location is reachable by antibodies, with high confidence. PROTAC: ubiquitination databases record sites on it; its protein half-life has been measured.
Gene: Protein-coding gene on chromosome 12 (123,620,406 to 123,633,766, reverse strand). Ensembl gene ENSG00000111361.
Subcellular location: Cytoplasm, cytosol
Subcellular location (Human Protein Atlas): Cytosol
Pathways (Reactome):
Metabolism of proteins: Recycling of eIF2:GDP
Gene Ontology:
Molecular function: guanyl-nucleotide exchange factor activity; identical protein binding; protein binding; translation initiation factor activity
Biological process: cytoplasmic translational initiation; oligodendrocyte development; positive regulation of translational initiation; T cell receptor signaling pathway; translational initiation; response to glucose; response to heat; response to peptide hormone
Cellular component: cytoplasm; eukaryotic translation initiation factor 2B complex; membrane; plasma membrane; cytosol
Genetic constraint (gnomAD): Loss-of-function variants: 30 observed, 38.4 expected, observed/expected ratio (o/e) 0.78, 90% interval 0.58 to 1.06. The upper end of that interval is the gene's LOEUF score, 1.06, which puts it in group 4 of 6, group 1 being the genes least tolerant of losing a copy. Missense variants: 271 observed, 394.81 expected, observed/expected ratio (o/e) 0.69, 90% interval 0.62 to 0.76. Synonymous variants: 139 observed, 149.54 expected, observed/expected ratio (o/e) 0.93, 90% interval 0.81 to 1.07.
Gene-disease validity (ClinGen):
ClinGen rates the evidence that EIF2B1 causes each of these diseases.
leukoencephalopathy with vanishing white matter 1 (autosomal recessive): Definitive. Any leukoencephalopathy with vanishing white matter in which the cause of the disease is a variation in the EIF2B1 gene.
Homologues: Orthologues: macaque EIF2B1 (99% identical), chimpanzee EIF2B1 (99% identical), dog EIF2B1 (96% identical), rabbit EIF2B1 (96% identical), guinea pig EIF2B1 (95% identical), mouse Eif2b1 (94% identical), rat Eif2b1 (92% identical), tropical clawed frog eif2b1 (78% identical), zebrafish eif2b1 (73% identical), Drosophila melanogaster eIF2Balpha (49% identical), Caenorhabditis elegans eif-2Balpha (42% identical). Paralogues in human: EIF2B4 (26% identical), EIF2B2 (22% identical), MRI1 (22% identical).
Diseases named in the same sentence as EIF2B1 in open-access papers:
EIF2B1 is named in the same sentence as 22 diseases in open-access papers, as found by Europe PMC text mining. Sharing a sentence is not in itself a finding about the gene and the disease. The quoted sentences say what the papers report.
Leukoencephalopathy (6 papers, 2015 to 2024). This term describes abnormality of the white matter of the cerebrum resulting from damage to the myelin sheaths of nerve cells. "Leukoencephalopathy with vanishing white matter (VWM) is a rare autosomal recessive leukoencephalopathy resulting from mutations in EIF2B1‐5." (PMID 36650674, 2023). "Loss-of-function mutations in the EIF2B1-5 genes are associated with the rare, frequently fatal neurological disorder, leukoencephalopathy with vanishing white matter (VWMD)." (PMID 35579296, 2022). "Vanishing white matter disease (VWM) is an inherited leukoencephalopathy in children attributed to mutations in EIF2B1–5, encoding five subunits of eukaryotic translation initiation factor 2B (eIF2B)." (PMID 30720246, 2019). "Besides, the impairment of stress response by mutations in EIF2AK2 –which encodes a eiF2α kinase–and eiF2B genes–EIF2B1 and EIF2B2– leads to leukoencephalopathy, hereby suggesting the importance of the UPR in CNS structure." (PMID 39071803, 2024).
Vanishing white matter disease (5 papers, 2019 to 2024). "Regarding variants in the EIF2B1-5 genes, most variants associated with ovarioleukodystrophy were missense variants, similar to those associated with classic VWMD." (PMID 39139316, 2024). "This review included clinical data from 20 cases of ovarioleukodystrophy due to variants in the EIF2B1-5 genes described worldwide, including one new case identified in Mexico." (PMID 39139316, 2024). "Ovarioleukodystrophy is an ultra-rare entity, and, to our knowledge, only 20 cases associated with variants in the EIF2B1-5 genes have been described worldwide through this systematic review." (PMID 39139316, 2024).
leukodystrophy (3 papers, 2017 to 2025). Leukodystrophies are a group of rare, progressive, metabolic, genetic diseases that affect the brain, spinal cord and often the peripheral nerves. "Vanishing White matter (VWM) is one of the more prevalent leukodystrophies, caused by biallelic pathogenic variants in any of the EIF2B1–5 genes." (PMID 40859278, 2025). "Although EIF2B1‐5 mutations are the main cause of leukodystrophy with POF, other genes have been described." (PMID 33245593, 2020).
diabetes (2 papers, 2022). "Several monogenic diabetes genes target translational initiation, in particular eIF2 complex (EIF2B1, EIF2S3, EIF2AK3), due to their impact on endoplasmic reticulum stress in β-cells." (PMID 36109769, 2022). "Recently, an increased incidence of heterozygous de novo missense variants in the EIF2B1 gene, which encodes eIF2Bα has been identified in patients with permanent neonatal diabetes mellitus (PNDM), a disorder resulting in early onset diabetes, typically diagnosed within the first 6 months of life." (PMID 35579296, 2022).
endometriosis (1 paper, 2021). The growth of functional endometrial tissue in anatomic sites outside the uterine body. "According to the RefFinder tool and the optimal number of reference genes determined using geNorm, EIF2B1 and POP4 were the two most stable genes for MenMSCs from women with and without endometriosis." (PMID 33686153, 2021). "Interestingly, we found the five most stable genes (EIF2B1, POP4, UBC, CASC3, and MRPL19) were not previously measured in endometriosis expression studies." (PMID 33686153, 2021).
meningioma (1 paper, 2011). A generally slow growing tumor attached to the dura mater. "Eight highest ranked reference genes (CASC3, EIF2B1, IPO8, MRPL19, PGK1, POP4, PPIA, and RPL37A) plus GAPDH and ACTB were then analyzed in 35 meningiomas, arachnoidea, dura mater and normal brain." (PMID 21806841, 2011). "RPL37A is the optimal single reference gene for normalization of gene expression in meningiomas and their control tissues, although the use of the combination of RPL37A and EIF2B1 would provide more stable results." (PMID 21806841, 2011). "For meningiomas and their normal control tissue the combination is RPL37A and EIF2B1." (PMID 21806841, 2011).
sarcoma (1 paper, 2022). A usually aggressive malignant neoplasm of the soft tissue or bone. "Dedifferentiated sarcoma is commonly characterized by an overexpressed chromosome region, 12q24, containing the gene EIF2B1, which encodes for the eukaryotic translation initiation factor 2B (eIF2Bα)." (PMID 36662211, 2022).
cancer (4 papers, 2019 to 2025). A tumor composed of atypical neoplastic, often pleomorphic cells that invade other tissues. "Within the set of genes that have a low standard deviation in all six-cancer types the genes that consistently have a lower expression relative to each other are EIF2B1, TP73 andSTX10." (PMID 31831960, 2019). "Moreover, by comparing the 13 survival-related gene lists, seven genes (SLK, API5, BTBD2, PTAR1, VPS37A, EIF2B1, and ZRANB1) were found to be associated with prognosis in a variety of cancers." (PMID 32300588, 2020). "EIF2B1 (Eukaryotic translation initiation factor 2B) is essential for the initiation of protein synthesis; its reduction could lead to a broad decrease in protein production, affecting various growth and survival pathways in cancer cells." (PMID 40090465, 2025). "These proteins, including AHCYL1, APLP2, CTNN1D, EIF2B1, LGALS1, and SGPL1, play vital roles in maintaining cellular functions such as cell adhesion, protein synthesis, and lipid metabolism, which are often perturbed in cancer cells." (PMID 40090465, 2025). "Several genes (B2M, EIF2B1, ELF1 and PSMC4; type 1 EC, and YWAZ, UBC, and PGK1; type 2 EC) were not identified in the combinations of five best genes for the two cancer sub-types (this study) suggesting that the transcriptome of these two EC sub-types may in fact be very different." (PMID 32439920, 2020).
tumor (2 papers, 2019 to 2025). "Tumour cell growth in secretome of activated PSCs caused a significant increase in the expression of proteins of translation initiation, such as translation initiation factor eIF-2B subunit alpha (eIF2B-1) and particularly eukaryotic translation initiation factor 4E (eIF4E)." (PMID 30923340, 2019).
genetic disorders (1 paper, 2011). "Of these genes, ATP6V0A2 [Ensembl:ENSCAFG00000007234] and EIF2B1 [Ensembl:ENSCAFG00000007434] are of special interest because they are involved in genetic disorders in humans." (PMID 21722374, 2011).
neurodegenerative disease (1 paper, 2015). A disorder of the central nervous system characterized by gradual and progressive loss of neural tissue and neurologic function. "A wide range of mutations in each of the five subunits of eukaryotic translation initiation factor 2B (eIF2B1-5) could lead to this fatal neurodegenerative disease." (PMID 25761052, 2015).
EIF2B1 also shares sentences with these, for which no sentence is quoted: neurological disorder (2 papers); Cerebroretinal vasculopathy (1); COVID-19 (1); dementia (1); Hypertension (1); metachromatic leukodystrophy (1); neonatal diabetes mellitus (1); ovarian dysfunction (1); permanent neonatal diabetes mellitus (1); schizophrenia (1); viral infection (1).